RN7SL457P (RNA, 7SL, cytoplasmic 457, pseudogene)
Gene: Miscellaneous RNA gene on chromosome 8 (33,715,784 to 33,716,070, forward strand). Ensembl gene ENSG00000263794.
Homologues: Orthologues: chimpanzee Metazoa_SRP (99% identical), macaque Metazoa_SRP (93% identical). Paralogues in human: RN7SL1 (84% identical), RN7SL2 (83% identical), RN7SL3 (82% identical), RN7SL218P (81% identical), RN7SL187P (81% identical), RN7SL803P (80% identical), RN7SL296P (80% identical), RN7SL336P (80% identical), RN7SL44P (80% identical), RN7SL481P (80% identical), RN7SL567P (80% identical), RN7SL126P (79% identical), and 703 more.